APOE (apolipoprotein E)
Diseases named in the same sentence as APOE in open-access papers (continued):
Sharing a sentence is not in itself a finding about the gene and the disease.
Alzheimer disease (continued). "Apolipoprotein E4 (APOE4), a well-known genetic risk factor of Alzheimer’s disease, has been studied for its potential role in PD-related cognitive impairment." (PMID 40052092, 2025). "For example, mutations in the BRCA1/2 genes are associated with a high risk of developing breast and ovarian cancer, and the apolipoprotein E (APOE) ε4 allele is associated with the risk of Alzheimer’s disease." (PMID 41155400, 2025). "The apolipoprotein E (APOE) ε4 allele is the strongest genetic risk factor for Alzheimer’s disease, yet the mechanisms linking APOE to amyloid-β (Aβ) pathology remain incompletely understood." (PMID 41037094, 2025). "The APOE ε4 allele increases the risk of Alzheimer disease through multiple mechanisms, including an increase in amyloid plaques, CAA, and in plaque-mediated tangle accumulation." (PMID 40475543, 2025). "Apolipoprotein E (APOE) is a crucial protein involved in fat metabolism in the human body that is associated with Alzheimer’s disease (AD)." (PMID 40806295, 2025). "Our scientific premise is based on the role of alleles of the apolipoprotein E (ApoE) gene in aging and Alzheimer’s disease." (PMID 40794785, 2025). "The ε4 allele of apolipoprotein E (APOE4) is the strongest genetic risk factor for Alzheimer's disease (AD), increasing AD risk about fourfold in ~ 34 million American and ~ 75 million European females." (PMID 41283974, 2025). "For example, the ε4 variant of apolipoprotein E (APOE) has been identified as a significant genetic risk factor for Alzheimer’s disease (AD) and a wide range of other neurodegenerative conditions." (PMID 40874237, 2025). "Alzheimer’s disease (AD) is a neurodegenerative disorder with the APOE ε4 allele as a key genetic risk factor." (PMID 40313365, 2025). "In the case of Alzheimer's disease, more than a factor of 10 separates Japanese versus Caribbean Hispanics for APOE ε4 homozygotes' associated risk of AD." (PMID 41282305, 2025). "Apolipoprotein E is characterized by different variants with neutral (ApoE3), protective (ApoE2), or detrimental (ApoE4) roles in Alzheimer's disease pathogenesis." (PMID 40637118, 2025). "The APOE genotype, a significant genetic risk factor of Alzheimer’s disease, has been shown to interact with VAMP2." (PMID 40003632, 2025). "APOE is a risk factor for dementia, and its effects depend on disease stage and genetic variants, particularly in Alzheimer’s disease." (PMID 40699836, 2025). "Certain genetic variants, such as the Apolipoprotein E (APOE) ε4 allele, have been associated with an increased risk of Alzheimer’s disease, the most common form of dementia." (PMID 40806031, 2025). "Genome-wide association studies have identified genes involved in the pathogenicity of both COVID-19 and Alzheimer ́s disease, namely the ε4 allele of the APOE gene." (PMID 40624305, 2025). "The main associated pathological isoform of APOE in AD is the APOE-ε4 genotype, which is the highest risk category for late-onset Alzheimer’s disease (LOAD), with the underlying mechanism of this link being both presynaptic and postsynaptic dysfunction." (PMID 40943177, 2025). "The apolipoprotein E (APOE) gene, particularly the ε4 allele associated with Alzheimer’s Disease risk, has been extensively studied in postoperative delirium." (PMID 41375722, 2025). "Key AD-related genes like App, ApoE, and Adam10 were notably affected, indicating that impaired neurogenesis contributes to memory loss in Alzheimer's disease." (PMID 40180804, 2025). "The APOE ε4 allele, a major genetic risk factor for Alzheimer’s disease, is consistently associated with a blunted response to DHA supplementation." (PMID 41515400, 2025). "Apolipoprotein E gene allele 4 status and amyloid-beta are accelerating factors for tau-related pathological changes in Alzheimer's disease." (PMID 41180953, 2025). "It has been reported that plasma levels of HAGH protein are associated with Alzheimer’s disease in carriers of apolipoprotein E." (PMID 40697080, 2025).
Alzheimer disease (continued). "Induced human neurons treated with ApoE4, a prevalent ApoE variant associated with Alzheimer’s disease, also show upregulation of DLK, which leads to enhanced transcription of APP and thus Aβ levels." (PMID 40067879, 2025). "Our study reveals a new connection between host genetic variation (specifically, APOE genotype) and the gut microbiome, which is associated with Aβ deposits—a key feature of Alzheimer’s disease." (PMID 41037094, 2025). "Classically, the APOE ε4 allele is known as one of the most common genetic determinants of Alzheimer's Disease (AD)." (PMID 41180817, 2025). "These associations were modulated by unmodifiable risk factors for Alzheimer’s disease, including older age, female sex and the APOE-ɛ4 genotype." (PMID 39723106, 2025). "The e2 allele of the APOE gene (APOEe2) is associated with a lower risk of developing Alzheimer’s disease (AD) but the mechanisms underlying its influence on the onset and progression of AD have not been elucidated." (PMID 40026419, 2025). "The Apolipoprotein E (ApoE) ε4 allele, as the major genetic risk factor for dementia, has been shown to have the most significant association with Alzheimer’s disease (the most common type of dementia) in East Asians." (PMID 40641975, 2025). "The apolipoprotein E (APOE) ɛ4 allele is the primary genetic risk factor that influences lipid metabolism and contributes to distinctive Alzheimer's disease pathologies, including increased hippocampal atrophy and accelerated cognitive decline." (PMID 40740432, 2025). "Alzheimer’s disease and related dementias are major public health challenges, with the apolipoprotein (APOE) ε4 allele being a significant genetic risk factor." (PMID 41035086, 2025). "Apolipoprotein E (APOE) genetic variation is the strongest genetic risk factor for late onset Alzheimer’s disease (LOAD)." (PMID 40666931, 2025). "The apolipoprotein E (ApoE) isoforms, central to Alzheimer’s disease susceptibility, exhibit distinct sialylation profiles: ApoE2 carries the highest sialic acid content, while ApoE4 contains the least." (PMID 41471108, 2025). "EVs were shown to reduce neural degeneration in cells treated with conditioned media of brain organoids derived from iPSCs of a sporadic AD patient with an APOE ε4/ε4 mutation that models neural degeneration in Alzheimer’s disease." (PMID 41007177, 2025). "Apolipoprotein E4 (ApoE4) genotype, hypertension, and biological sex are critical risk factors for Alzheimer's disease and related dementias." (PMID 41041548, 2025). "Genetic studies reveal specific variants of the Apolipoprotein E (APOE) gene implicated in VaD, mirroring its role in Alzheimer’s Disease." (PMID 40291849, 2025). "At later ages, those with one copy of the APOE-ε4 allele have approximately three times increased risk of Alzheimer’s disease, and those with two copies of ε4 have 8–14 times increased risk, compared to the ε3/ε3 genotype." (PMID 41264616, 2025). "The apolipoprotein E type ∊4 allele (ApoE4) is known as the strongest genetic risk factor for Alzheimer’s Disease (AD)." (PMID 39913635, 2025). "The APOE ε4 allele, which is present in about 16% of the population, carries the highest genetic risk factor for late-onset Alzheimer’s disease." (PMID 40863490, 2025). "Previous studies have implicated HMGCR in Alzheimer’s disease (AD) as a genetic modifier of risk and cognitive decline, comparable to APOE, the main cholesterol transporter in the brain." (PMID 41037108, 2025). "Analysis of genome‐wide association studies of pathology‐confirmed Alzheimer's disease gives large signals at the APOE locus and many low odds ratio associations at microglial loci." (PMID 40600356, 2025). "Despite having less healthy lifestyles, higher rates of APOE ɛ4 allele carriage and smaller brains, night/shift workers had lower levels of Alzheimer’s disease pathology as measured by both amyloid PET and plasma p-tau217." (PMID 40677699, 2025).
Alzheimer disease (continued). "The apolipoprotein E4 (APOE4) gene increases the risk of Alzheimer’s disease, depression, and anxiety." (PMID 39833961, 2025). "APOE ε4 genotype is considered a risk factor in late-onset Alzheimer’s disease in both familial and sporadic cases." (PMID 41149812, 2025). "Around 25% of the population has one copy of APOE-4, which can both contribute to lowering the age of onset and increase the risk of developing Alzheimer’s dementia." (PMID 41368162, 2025). "Our polygenic risk score included APOE variants, which are the strongest known genetic determinants of Alzheimer’s disease risk." (PMID 41329349, 2025). "There are also complex APOE genotype × sex interactions such that female APOE4 carriers have a greater risk of developing Alzheimer’s disease than male carriers." (PMID 39658276, 2025). "The association between APOE alleles and ARIA, a known adverse reaction in Alzheimer’s disease patients treated with anti-amyloid monoclonal antibodies, has led to the inclusion of APOE genotyping among conventional pharmacogenetic tests." (PMID 40761402, 2025). "Clu currently ranks as the third major risk factor associated with Alzheimer’s disease (AD), albeit with a considerably smaller effect size compared to the ApoE gene." (PMID 40806404, 2025). "Although apolipoprotein E (ApoE) ε4 is a well-established risk factor for Alzheimer disease, its role in the development of post-stroke cognitive impairment (PSCI) remains uncertain." (PMID 40349252, 2025). "Genetic risk factors, notably the APOE ε4 allele, contribute significantly, especially in Alzheimer's disease and particularly among women." (PMID 40970035, 2025). "Apolipoprotein E4 (ApoE4) has been identified as a significant genetic risk factor for late-onset Alzheimer’s disease, as it has been associated with reduced BDNF levels and inhibited BDNF mRNA expression." (PMID 40430064, 2025). "This isoform is the most significant genetic risk factor for late-onset Alzheimer’s disease and is known to alter ApoE structure, lipid metabolism, and amyloid-beta (Aβ) interaction dynamics." (PMID 40892789, 2025). "The common genetic risk factor for late-onset Alzheimer’s disease, the apolipoprotein E (APOE) ε4 allele, has specifically been associated with increased risk of coronary heart disease and CVD, as well as detrimental effects on white matter." (PMID 40641621, 2025). "The apolipoprotein E (APOE) 4 allele is the strongest known genetic risk factor for Alzheimer’s disease and evidence suggests the risk is greater in women than in men." (PMID 40248334, 2025). "Among anthropoids, humans uniquely possess ApoE isoforms that modulate Alzheimer’s disease (AD) risk and brain aging." (PMID 40475510, 2025). "The association between the E4 allele of the APOE apolipoprotein gene and Alzheimer’s disease is well established." (PMID 40722695, 2025). "Treatments aimed at APOE, such as APOE modulators and lipid-lowering drugs, show promise in correcting cholesterol deregulation and decreasing the risk of Alzheimer’s disease, especially among APOE ε4 carriers." (PMID 41454181, 2025). "Only 2–3% of the population have two copies of APOE-4, which can significantly increase the risk of developing Alzheimer’s dementia." (PMID 41368162, 2025). "ApoE and ApoJ (known also as clusterin) are associated with the development of neurodegenerative diseases, including Alzheimer’s disease, and are also important determinants of the lipid profile and cardiovascular health." (PMID 40137160, 2025). "But is tele‐genetic counseling (GC) for APOE genotype disclosure for Alzheimer's disease (ad) risk as effective as onsite interventions?" (PMID 41035143, 2025). "Lewy body dementia (LBD) shares genetic risk factors with Alzheimer's disease (AD), including apolipoprotein E (APOE), but is distinguishable at the genome‐wide level." (PMID 39853853, 2025).
Alzheimer disease (continued). "Despite having less healthy lifestyles, higher rates of APOE ɛ4 allele carriage and smaller brains, night/shift workers had lower levels of Alzheimer’s disease pathology and lower rates of all-cause (excluding vascular) dementia." (PMID 40677699, 2025). "The robust association of APOE-ε4 with cognitive impairment across diverse populations reinforces its role as a significant genetic risk factor for Alzheimer’s disease and related cognitive declines." (PMID 41264616, 2025). "One major risk factor for sporadic late-onset Alzheimer’s disease (LOAD) is the APOE gene, and specifically the ε4 allele, because of its location on chromosome 19 in a peak linkage region." (PMID 38967905, 2025). "ApoE is a well-established genetic risk factor for Alzheimer’s disease, but the role of B-vitamins in modifying this risk remains largely unexplored." (PMID 40717068, 2025). "Beyond age, the apolipoprotein E (APOE) gene is the greatest risk determinant of late-onset Alzheimer’s disease (LOAD) in which symptoms develop after the age of 65." (PMID 40382659, 2025). "This link is particularly evident in patients carrying the most common genetic risk factor for late onset Alzheimer’s disease: apolipoprotein E-ε4 (APOE4), who show a rapid decline in cerebral blood flow in old age, before developing AD2." (PMID 39880935, 2025). "Alzheimer's disease (AD) is frequently concomitant, with the ε4 allele of apolipoprotein E (ApoE) gene (ApoE) being considered a mutual risk." (PMID 40474363, 2025). "APOE variants are the largest monogenetic risk modifiers of Alzheimer's disease and have more recently been implicated in modulating additional phenotypes ranging from cardiovascular disease to tumor and infection immunity." (PMID 40384567, 2025). "The ε4 allele of APOE (APOE4) is the strongest genetic risk factor for late-onset Alzheimer’s disease (AD), and certain lipids are closely linked to AD pathology." (PMID 41022324, 2025). "Among individuals with a genetic risk of Alzheimer disease, ie, carriers of the APOE e4 allele, better CVH was significantly associated with lower serum levels of NfL." (PMID 40067299, 2025). "These associations were moderated by APOE ε4 status, suggesting a distinct pattern in individuals genetically predisposed to Alzheimer’s disease." (PMID 41268178, 2025). "Understanding the mechanisms behind this association, particularly in the context of APOE-ɛ4, is crucial for developing targeted interventions to mitigate the impact of chronic pain on cognitive function and Alzheimer’s disease progression." (PMID 40496670, 2025). "The genetic profile of apolipoprotein E (APOE) is a known risk factor for Alzheimer’s Disease in older populations." (PMID 40242320, 2025). "Variation in the Apolipoprotein E (APOE) gene is a major genetic risk factor for Alzheimer’s disease." (PMID 41264616, 2025). "A study of 56,864 individuals from the Alzheimer’s Disease Sequencing Project (ADSP) was able to identify seven individuals who were heterozygous carriers of APOE LOF variants." (PMID 41123760, 2025). "The apolipoprotein E allele ε4 is the most well-known predisposing genetic risk factor for Alzheimer's disease (AD)." (PMID 40171450, 2025). "In Alzheimer’s disease, evidence of the huge discrepancy in disease risk depending on APOE status, and the differential biological effects such as amyloid deposition and microglial activation make it likely that such interactions do exist." (PMID 41176580, 2025). "Higher whole plasma apoE levels and higher apoE levels in HDL were unassociated with dementia or Alzheimer disease risk." (PMID 40353050, 2025). "These and related findings reinforce the view that APOE polymorphisms contribute to Alzheimer’s disease susceptibility by affecting both beta-amyloid deposition and tau protein processing." (PMID 40869138, 2025). "The apolipoprotein E epsilon 4 allele (APOE4) is one of the most influential genetic risk factors for late-onset Alzheimer’s disease (LOAD)." (PMID 40842730, 2025).
Alzheimer disease (continued). "Among the identified genetic factors, the ε4 allele of the apolipoprotein E gene remains the most significant risk factor for late-onset Alzheimer’s disease." (PMID 40869138, 2025). "The presence of one APOE ε4 allele raises the risk of developing late-onset Alzheimer’s disease approximately three- to fourfold, whereas homozygosity for the ε4 allele confers a nine- to fifteenfold increase in risk." (PMID 40869138, 2025). "In contrast, ApoE4 mice express the human apolipoprotein E4 (APOE4) allele, the strongest genetic risk factor for late-onset Alzheimer’s disease." (PMID 40705152, 2025). "APOE*4 is the strongest, common genetic risk factor for late-onset Alzheimer’s disease (AD) with widespread and cell-type-specific impact on disease pathogenesis." (PMID 41404291, 2025). "Among these, the ApoE ε4 allele is particularly notable due to its strong association with an increased risk of late-onset Alzheimer’s disease (AD), the most common form of dementia." (PMID 40349252, 2025). "The APOE ε4 allele is the strongest genetic risk factor for late-onset Alzheimer’s disease (AD) and is associated with increased risk of amyloid-related imaging abnormalities (ARIA) during anti-amyloid therapy." (PMID 40671162, 2025). "Age, sex, and apolipoprotein E (APOE) are the strongest risk factors for late-onset Alzheimer disease (AD)." (PMID 40067298, 2025). "Apolipoprotein E allele 4 (APOE ε4) is the main genetic risk factor for late‐onset Alzheimer's disease (AD), but most evidence comes from White populations in high‐income countries." (PMID 41268805, 2025). "Among the various genetic factors involved, Apolipoprotein E (APOE) plays a pivotal role in the risk of Alzheimer’s disease (AD)." (PMID 41226628, 2025). "Consistent with the important role of ApoE in brain homeostasis and injury repair, APOE polymorphisms have been reported to be associated with Alzheimer’s disease (AD) and age-related cognitive decline." (PMID 40026711, 2025). "Decreased expression of sirtuin 1 (SirT1) has been implicated in Alzheimer’s disease (AD), and as we previously reported, is related to transcriptional repression by the major risk factor for sporadic AD, apolipoprotein E4 (ApoE4)." (PMID 40269061, 2025). "The behavioural abnormalities of ApoE-deficient mice, which are genetically modified mice artificially deficient in ApoE, have been investigated in detail, and it has been reported that they can serve as a model of Alzheimer’s disease (AD)." (PMID 40026711, 2025). "Alzheimer’s disease (AD) disproportionately and uniquely affects females, and these sex differences are further exacerbated by the presence of Apolipoprotein (APOE) ε4 alleles, the top genetic risk factor for late-onset AD." (PMID 39910616, 2025). "In terms of allele frequency and Alzheimer’s disease (AD) risk, APOE ε3 is the most prevalent allele and is considered neutral concerning AD susceptibility." (PMID 40275327, 2025). "Apolipoprotein E (APOE) alleles play distinct roles in the pathogenesis of Alzheimer’s disease (AD), with APOEε4 being the strongest genetic risk factor for late-onset AD, while APOEε2 appears protective." (PMID 40722268, 2025). "Among genetic markers, the apolipoprotein E (APOE) gene stands out as the most robust predictor of late-onset Alzheimer’s disease (AD) and vascular dementia risk." (PMID 41264567, 2025). "APOE ε4 is the strongest genetic risk factor for late-onset Alzheimer’s disease (AD), but its contribution to disease pathogenesis remains incompletely understood." (PMID 40709278, 2025). "Apolipoprotein E (ApoE) is a key genetic risk factor in the complex landscape of Alzheimer’s disease (AD), especially in its late-onset sporadic form." (PMID 39944166, 2025). "Cognitive decline precedes and predicts functional decline in aging and Alzheimer’s disease (AD), a progressive neurodegenerative disease for which the APOE gene is among its greatest risk." (PMID 41439935, 2025).